ITGB6 (integrin subunit beta 6)
Diseases named in the same sentence as ITGB6 in open-access papers (continued):
Sharing a sentence is not in itself a finding about the gene and the disease.
gastric cancer (continued). "All these results indicated that ITGB6 was present in both serum and tumor tissue of gastric cancer patients, and serum ITGB6 may serve as a potential biomarker for advanced gastric cancer." (PMID 34796117, 2021). "Moreover, combined serum ITGB6 and CEA levels significantly improved the efficacy for the risk stratification of gastric cancer." (PMID 34796117, 2021). "Furthermore, ITGB6 expression in tumor tissues was correlated with serum ITGB6 levels in advanced gastric cancer." (PMID 34796117, 2021). "Results showed that ITGB6 could be detected in the serum of gastric cancer patients, which ranged from 0-5.16ng/ml, and serum ITGB6 levels were significantly increased in gastric cancer patients." (PMID 34796117, 2021). "High ITGB6 expression indicated a poor prognosis, and nomogram including serum ITGB6 expression could predict the prognosis of gastric cancer patients effectively." (PMID 34796117, 2021). "Previous research demonstrated that elevated ITGB6 in gastric cancer tissues might serve as a potential biomarker for tumor progression and the prognosis of patients." (PMID 34796117, 2021). "Furthermore, to evaluate the predictive value of ITGB6 on the prognosis of gastric cancer patients, time-dependent ROC analysis was conducted and the AUC was 0.685 (95% CI: 0.568-0.803, sensitivity: 69.1%, specificity: 68.0%)." (PMID 34796117, 2021). "The present study investigated whether serum ITGB6 level serves as a novel tumor biomarker for gastric cancer patients." (PMID 34796117, 2021). "All these results verified that serum ITGB6 may serve as an unfavorable prognostic indicator for gastric cancer." (PMID 34796117, 2021). "Furthermore, combined serum ITGB6 and CEA levels contributed to the risk stratification and prognostic prediction for gastric cancer patients." (PMID 34796117, 2021). "Univariate analysis suggested that depth of invasion, TNM stage, neurovascular invasion, ITGB6 and CEA levels might be associated with the prognosis for gastric cancer patients (P<0.1)." (PMID 34796117, 2021). "Moreover, as more and more gastric cancer patients receive chemotherapy before or after surgery nowadays, the effect of chemotherapy on both serum and tissue ITGB6 expression is also deserved further investigation." (PMID 34796117, 2021). "Simultaneously, experimental results showed that after inhibiting Rac1 activity, the role of ITGB6 in gastric cancer cell activity, migration, and invasion disappeared, suggesting that ITGB6 might play a role in the proliferation, migration, and invasion of gastric cancer cells through Rac1." (PMID 38344200, 2024). "Additionally, subsequent in vitro experiments preliminarily demonstrated that ITGB6 and Rac1 promoted the proliferation, migration and invasion of gastric cancer cells, and ITGB6 may functions via targeting Rac1." (PMID 38344200, 2024). "Here we identified serum ITGB6 level may serve as a novel tumor biomarker for gastric cancer." (PMID 34796117, 2021). "To investigate whether serum ITGB6 could be used for tumor surveillance and monitoring of tumor recurrence during the follow-up of gastric cancer patients, we detected the expression of serum ITGB6 before and after surgery, and followed up the patients for 6 months in the prospective cohort." (PMID 34796117, 2021). "Multivariate analysis confirmed that TNM stage, ITGB6 and CEA levels were independent prognostic factors for gastric cancer patients." (PMID 34796117, 2021). "All these results indicated that combined ITGB6 and CEA levels may improve the specificity of predicting clinical outcomes of gastric cancer patients." (PMID 34796117, 2021).
oral squamous cell carcinoma (5 papers, 2015 to 2022). "ITGB6 is highly expressed in oral squamous cell carcinoma and can be used as a diagnostic biomarker." (PMID 33335550, 2020). "We previously reported that the promoter region of the human ITGB6 gene contains STAT3 binding sites, and the basal rate of ITGB6 expression in oral squamous cell carcinoma cells is primarily defined by STAT3." (PMID 36299623, 2022). "Using chromatin immunoprecipitation assays, this study has demonstrated, for the first time, that transcription factors STAT3 and C/EBPα are involved in the positive regulation of ITGB6 transcription in oral squamous cell carcinoma cells." (PMID 25816241, 2015).
asthma (4 papers, 2017 to 2022). "ITGB6 expression was negatively associated with basement membrane thickness in asthma (R2 = 0.1801, p = 0.04) and negatively associated with Epithelial area/Pi in both groups combined (R2 = 0.1158, p = 0.02)." (PMID 29228930, 2017). "There was an association between ITGB6 expression and Collagen/Pi in asthma that did not quite reach significance." (PMID 29228930, 2017). "On the other hand, all three of these ITGB6(+)MP subtypes, especially Snail(+)ITGB6(+)MPs and αSMA(+)ITGB6(+)MPs, were significantly higher in CRSwNP cases with history of prior surgery than those without prior surgery, independent of asthma status." (PMID 34769139, 2021).
colorectal cancer (4 papers, 2021 to 2024). A primary or metastatic malignant neoplasm that affects the colon or rectum. "ITGB6, which is highly expressed in colorectal cancer, is associated with a poor prognosis." (PMID 34976806, 2021). "Most of previous research mainly focus on tissue-expressed ITGB6 and as far as we know, only one study detected serum ITGB6 expression in patients with colorectal cancer, which revealed that serum ITGB6 may serve as a potential biomarker for diagnosis and surveillance of colorectal cancer." (PMID 34796117, 2021). "Many of the other differentially expressed proteins have been described in colorectal cancer progression, including integrins of which ITGA11, ITGAV (also among the top 10 hub proteins) and ITGB6 were altered in this study." (PMID 39167197, 2024). "Previous study also demonstrated that integrin αvβ6 may contribute to targeted liver metastasis of colorectal cancer via the SDF-1/CXCR4 axis, and we should notice the phenomenon that serum ITGB6 expression was markedly increased in patients with liver metastasis." (PMID 34796117, 2021).
periodontal disease (4 papers, 2017 to 2023). "We have also shown previously that cytokines associated with periodontal disease or purified lipopolysaccharides from P. gingivalis, Tannerella forsythia and T. denticola were unable to suppress ITGB6 expression." (PMID 28667248, 2017). "In addition, patients with ITGB6 mutations can develop severe periodontal disease." (PMID 36299623, 2022). "Identification of more ITGB6 patients and further functional studies should be performed to validate the relationship between ITGB6 and periodontal disease." (PMID 37041139, 2023). "The presence of ITGB6 is essential for periodontal health, as its low expression in the gingival epithelium is related to the development of periodontal diseases." (PMID 36299623, 2022). "Studies have confirmed that biofilm components and FSL-1 can downregulate ITGB6 expression in the pocket epithelium, thus, promoting an epithelial cell-driven proinflammatory response in periodontal disease." (PMID 36299623, 2022). "Moreover, the Itgb6−/− mice developed periodontal disease exhibiting epithelial inflammation, pocket formation, and alveolar bone loss." (PMID 37041139, 2023). "Their expression in Itgb6−/− mice also remanined unchanged, indicating that they are not critically involved in the progression of periodontal disease." (PMID 28667248, 2017).
prostate carcinoma (4 papers, 2021 to 2024). A carcinoma that arises from epithelial cells of the prostate gland. "sEVs were engineered to carry ITGB6-specific siRNAs and were shown to inhibit adhesion and migration of recipient prostate cancer cells." (PMID 38307935, 2024). "Small extracellular vesicle-mediated transfer of ITGB6-targeting siRNAs to prostate cancer cells inhibit adhesion and migration on LAP-TGFβ1." (PMID 35188070, 2022). "We compared the expression levels of eight integrin subunits (ITGA2, ITGA5, ITGAV, ITGB1, ITGB3, ITGB4, ITGB5, and ITGB6), HOXB13, HOXA11-AS, CCL2, CXCL12, and IBSP in prostate cancer tissues that had metastasized to bone, lymph nodes, lungs, liver, and other organs." (PMID 33514011, 2021).
cervical cancer (3 papers, 2018 to 2024). A primary or metastatic malignant neoplasm involving the cervix. "This was also observed for cervical cancer cells upon silencing of ITGB6 through inactivation of the JAK/STAT3 signaling pathway." (PMID 38890650, 2024). "Silencing ITGB6 inhibits the proliferation, migration and invasion of cervical cancer cells and promotes apoptosis by inhibiting the JAK/STAT signaling pathway." (PMID 36267977, 2022).
colitis (3 papers, 2021 to 2025). Inflammation of the colon. "In the present study, integrin β6 deficient mice were generated, which showed that ITGB6 knockout significantly reduced susceptibility to DSS-induced colitis." (PMID 37223685, 2023). "Future studies are warranted to investigate the underlying mechanisms by which ITGB6 promotes the immune response in DSS‐induced colitis in mice." (PMID 33491282, 2021). "Overall, these results suggested that ITGB6 influenced susceptibility to acute colitis in mice and exacerbated the severity of acute DSS‐induced colitis." (PMID 33491282, 2021). "In order to investigate the role of integrin β6 in IBD, ITGB6-knockout (β6-KO) and wild-type (WT) mice model of acute colitis was constructed by the presence of 2.5% DSS solution." (PMID 37223685, 2023). "Unsurprisingly, we found that ITGB6 Tg mice exhibited increased susceptibility to acute and chronic DSS‐induced colitis." (PMID 33491282, 2021). "Survival analyses revealed that ITGB6 transgene expression correlated with poor prognosis in DSS‐induced colitis." (PMID 33491282, 2021). "Conditional ITGB6 transgene expression exacerbated experimental colitis in mouse models of acute and chronic dextran sulphate sodium (DSS)‐induced colitis." (PMID 33491282, 2021). "We further generated conditional ITGB6 transgenic mice (Villin1‐ITGB6 Tg), and found that ITGB6 Tg mice exhibited increased susceptibility to acute and chronic DSS‐induced colitis." (PMID 33491282, 2021). "Taken together, these results demonstrated that ITGB6 transgene expression aggravated chronic DSS‐induced colitis in mice." (PMID 33491282, 2021). "However, the exact molecular mechanisms by which ITGB6 exacerbates DSS‐induced colitis require further exploration." (PMID 33491282, 2021). "Therefore, in this study, we generated a Tg mouse conditionally overexpressing human ITGB6 in IECs, and a validated DSS‐induced colitis model mimicking the complex UC seen in patients to explore the role of ITGB6 in IBD progression." (PMID 33491282, 2021). "Therefore, in this part, we investigated the role of ITGB6 in the recruitment of inflammatory cells in a DSS‐induced colitis model." (PMID 33491282, 2021). "Furthermore, very-early-onset colitis and brain abnormalities have been described in three families harboring an integrin alpha-v variant (ITGAV) and in a patient with homozygous integrin β-6 polymorphism (ITGB6)." (PMID 40918109, 2025). "Collectively, these data suggested that the ITGB6 transgene dysregulated the secretion of pro‐inflammatory cytokines, upregulated the expression of integrin ligands and the phosphorylation of Stat1 in DSS‐induced colitis in mice, which might contribute to DSS‐induced colitis." (PMID 33491282, 2021). "Although Kindlin‐1 promotes ITGB6‐mediated TGF‐β activation and release, we didn't identify the significant expression difference of Kindlin‐1 between the colon of Tg mice and WT mice in DSS‐induced colitis model (data not shown)." (PMID 33491282, 2021).
dilated cardiomyopathy (3 papers, 2013 to 2019). Cardiomyopathy which is characterized by dilation and contractile dysfunction of the left and right ventricles. "In the close examination, 3 genes (Itgb6, Cacna2d3, and Cacna1c) were downregulated in 2-week-old cKO hearts, compared to 15 genes downregulated in KEGG_dilated cardiomyopathy pathway in 6-week-old cKO." (PMID 31787756, 2019). "Downregulated canonical pathways included those involved in arrhythmogenic, hypertrophic, and dilated cardiomyopathy signaling (e.g., Itgb6, Cacna1s, and Hadh), fatty acid metabolism, and peroxisome proliferator-activated receptor (PPAR) signaling (e.g., Acaa2, Cpt2, and Acsl6)." (PMID 25744495, 2015). "Moreover, in dilated cardiomyopathy pathway core enrichment, integrins (Itga1, Itga10, Itga8 and Itgb6) and cellular components of troponin system (Tnni3, Tnnc1 and Tnnt2) appeared modulated, besides Cox and Myh genes." (PMID 24252798, 2013).
lymph node metastasis (3 papers, 2016 to 2025). "Higher ITGAV and ITGB1 expression were associated with lymph node metastasis and extrathyroidal extension, while ITGB6 expression positively correlated with lymph node metastasis, advanced stage, and extrathyroidal extension." (PMID 40423510, 2025). "The data from this study also indicate that patients with high ITGB6 expression had significantly higher percentage of lymph node metastasis." (PMID 27184932, 2016).
melanoma (3 papers, 2019 to 2025). A malignant, usually aggressive tumor composed of atypical, neoplastic melanocytes. "SNP rs7563677 at 2q24.2 is an eQTL for ITGB6, representing a putatively novel drug target for KC, with an associated drug STX-100 currently in a Phase I clinical trial for melanoma." (PMID 31174203, 2019). "Previous studies have identified abnormal expression of ITGB6 in SK-Mel-28 human melanoma cells." (PMID 34660316, 2021).
Obesity (3 papers, 2014 to 2018). Accumulation of substantial excess body fat. "Endevour ranked Ly75 (lymphocyte antigen 75) and Itgb6 (integrin beta 6) as the top two candidate genes for Pbwg1.5 using training genes related to obesity." (PMID 25398139, 2014). "Therefore, the Ly75 and Itgb6 genes with immune function may be good candidate genes for our Pbwg1.5 that shows prevention of obesity when mice are fed both low-fat standard and high-fat diets." (PMID 25398139, 2014).
breast invasive carcinoma (2 papers, 2016 to 2024). "In addition, integrin β6 (ITGB6) is of prognostic value in invasive breast cancers, particularly in HER2+ subtype." (PMID 27184932, 2016). "Together, these data provide valuable insights into the differential expression patterns of ITGB6, ERBB2, RAB5A, RAB7A, and GDI2 in breast invasive carcinoma." (PMID 39630893, 2024).
breast tumor (2 papers, 2016 to 2018). "ITGB6 is a prognostic marker associated with breast tumor progression." (PMID 29719590, 2018). "Since, multiple members of this pathway significantly correlate with ITGB6 mRNA expression, this association is suggestive of a potential role of coupled αvβ6‐HER2 signaling in mediating migration and invasion of breast tumor cells through this pathway." (PMID 27184932, 2016).
esophageal squamous cell carcinoma (2 papers, 2021 to 2025). Esophageal squamous cell carcinoma (ESCC) is a type of esophageal carcinoma (EC) that can affect any part of the esophagus, but is usually located in the upper or middle third. "Membranous β6-integrin (ITGB6) expression was analyzed in 306 specimens of human esophageal squamous cell carcinoma (ESCC) obtained by immunohistochemistry (IHC) from 100 patient cases (1, 37, 58, and 4 of grade G1, G2, G3, and G4, respectively)." (PMID 40540027, 2025).
gastric tumor (2 papers, 2018 to 2024). "We have observed that ITGB6 exhibits higher expression in gastric tumor tissues and lymph node metastasis, compared to adjacent non-cancerous tissues and lymph node metastasis negative." (PMID 38344200, 2024). "The correlation between the expression of ITGB6 and Rac1 in human gastric tumor tissues (r =0.285, P <0.001)." (PMID 38344200, 2024).
heart failure (2 papers, 2024 to 2025). Inability of the heart to pump blood at an adequate rate to meet tissue metabolic requirements. "Other important up-regulated genes were Fxyd2 (FXYD domain-containing ion transport regulator 2), an important regulator of the Na+ transport, and Itgb6 (myo-inositol 1-phosphate synthase A1), involved in resynchronization following heart failure." (PMID 38534766, 2024). "These four genes CAMTA2, ITGB6, NFATc2, and XDH are all related to heart failure, fibrosis, and cardiovascular disease." (PMID 40181955, 2025).
liver fibrosis (2 papers, 2019 to 2025). "Among the seven potential biomarkers FABP3, GALNT5, GPR84, ITGB6, MYEOV, PLEKHS1, and STRA6, we are particularly interested in GPR84 and STRA6 because they link to liver fibrosis that is a major risk factor in HCC and an independent risk factor of recurrence after hepatectomy." (PMID 31828095, 2019). "In accordance with the findings that blocking integrins with small molecules can hold back TGF-β signal and prevent liver fibrosis in mice, our findings confirmed that CWHM-12 inhibited the activation of TGF-β1 by blocking ITGB6 expression, thus affecting the expression of ALP." (PMID 40680053, 2025).
oral cancer (2 papers, 2019 to 2021). "According to our data, the expression level of the ITGB6 gene, whose overexpression is known to facilitate EMT and is associated with the invasiveness of oral cancer cells, decreases in cells expressing PDX1." (PMID 34503200, 2021). "TGF-β1 positively regulated ITGB6 expression in oral cancer cells and gingival keratinocytes that may participate in cancer invasion and periodontal inflammation, respectively." (PMID 31591384, 2019).
prostate tumors (2 papers, 2022 to 2024). "Here, we report that transcript levels of ITGB6 (encoding the β6 integrin subunit) are significantly increased in metastatic castrate-resistant androgen receptor-negative prostate tumors compared to androgen receptor-positive prostate tumors." (PMID 35188070, 2022). "ITGB6 encoded the β6 integrin subunit, with significantly higher expression observed in metastatic castrate-resistant androgen receptor-negative prostate tumors compared to androgen receptor-positive tumors." (PMID 38877472, 2024).
Atrophy (1 paper, 2024). Any weakening or degeneration, especially through lack of use. "Genetic variants associated with decreased levels of pathogenic proteins ITGB6 (rs8099840), TLR5 (rs1403631, rs75118229), F7 (rs6046), HERC5 (rs406936) and MGA (rs704) were associated with preserved brain volumes over time, including in regions susceptible to infection-specific atrophy." (PMID 39143319, 2024).
cardiomyopathy (1 paper, 2019). A disease of the heart muscle or myocardium proper. "We uncovered genomic regions of selective sweeps in the LBP and BPI genes (Salmonella infection) and the TTN and ITGB6 genes (cardiomyopathy), among several candidate genes." (PMID 31440273, 2019). "We further confirmed the ITGB6 (Integrin Subunit Beta 6) and TTN (Titin) genes among the several genes showing selection signals in the three cardiomyopathy pathways." (PMID 31440273, 2019). "Therefore, we further investigated patterns of nucleotide diversity, linkage disequilibrium, haplotype diversity, and Fst of LBP, BPI, ITGB6, and TTN genes, among KNG’s candidate genes enriched in Salmonella infection and cardiomyopathy pathways." (PMID 31440273, 2019).
chronic obstructive pulmonary disease (1 paper, 2014). A chronic and progressive lung disorder characterized by the loss of elasticity of the bronchial tree and the air sacs, destruction of the air sacs wall, thickening of the bronchial wall, and mucous accumulation in the bronchial tree. "Disruption of ITGB6 function has been linked with aged-related chronic obstructive pulmonary disease (COPD)." (PMID 24319098, 2014).
clear cell carcinoma (1 paper, 2019). "Five most downregulated genes in clear cell carcinoma include, ITGB6 (−9.09-fold), MUC1 (−5.00-fold), CDH1 (−3.57-fold), HIF1A (−2.27-fold) and FOS (−1.96-fold)." (PMID 30863721, 2019).